APOL1 (apolipoprotein L1)
Diseases named in the same sentence as APOL1 in open-access papers (continued):
Sharing a sentence is not in itself a finding about the gene and the disease.
Hypertension (continued). "This randomized clinical trial determines the effects of testing and disclosing APOL1 genetic results on patients of African ancestry with hypertension and their clinicians." (PMID 35244702, 2022). "In univariable analysis, APOL1 high-risk genotypes, West African ancestry, age, sex, prior AIDS, lower CD4 cell count, HIV viral load, anti– hepatitis C virus, diabetes, hypertension, and cardiovascular disease were associated with ESKD." (PMID 35497797, 2022). "This trial tested the effects of disclosing APOL1 genetic results to patients of African ancestry with hypertension and their PCPs." (PMID 35244702, 2022). "Third, APOL1 variants lead to both hypertension and CKD and the latter is impacted both by hypertension and the second hit." (PMID 31929905, 2019). "The APOL1 risk genotypes, including G1, were identified in admixture mapping for ESKD attributed to hypertension, FSGS or HIV, and associations have been replicated in population studies although not at the genome-wide significant level." (PMID 31178898, 2019). "In view of these studies including ours, a functional role of APOL1 in vasculorpathology, hypertension and kidney disease is worth exploring." (PMID 26112018, 2015). "Several studies have linked apolipoproteins (APOA1, APOB and APOL1) with CKD and hypertension." (PMID 38402394, 2024). "We also analyzed the associations between APOL1 high-risk genotypes and ESKD/renal impairment in models that included hypertension; these also yielded similar, albeit somewhat lower, ORs and with exclusion of the correction for ethnicity from the eGFR calculations." (PMID 35497797, 2022). "A large study of African Americans reported an association between SCT and incident ESKD independent of age, hypertension, and diabetes (hazard ratio 2.03), a risk of similar magnitude as posed by APOL1 high-risk genotypes." (PMID 35257059, 2022). "Risk variants in the apolipoprotein L1 (APOL1 [OMIM 603743]) gene on chromosome 22 are common in individuals of West African ancestry and confer increased risk of kidney failure for people with African ancestry and hypertension." (PMID 35244702, 2022). "More than 50 genetic variants have been identified that are potentially associated with the decline of kidney function and the development of hypertension and renal injury in various studies, among which the most frequently identified gene variants are UMOD, MYH9, APOL1, SHROOM3, RAB38, and DAB2." (PMID 33377622, 2021). "The association between mutations in APOL1 and hypertension is complex, and it could be explained by three possible relationships: first, APOL1 variants lead to CKD which in turn leads to hypertension." (PMID 31929905, 2019). "This suggests that the mechanism through which APOL1 mutations lead to kidney disease is not due to more prevalent or more severe hypertension." (PMID 31532792, 2019). "It is possible that blood pressure differences do exist between those with and without APOL1 risk alleles with more severe hypertension, or in those with overt kidney disease." (PMID 31532792, 2019). "In this study we had the opportunity to evaluate APOL1 risk allele carriers with mild to moderate essential hypertension, without overt kidney disease, and have gained some new insights as to their clinical characteristics." (PMID 31532792, 2019). "Data from the African American Study of Kidney Disease and Hypertension revealed an association between GSTM1 inactive genotypes and accelerated progression of CKD in a cohort of 692 Black Americans with hypertensive kidney disease, with worse progression in APOL1 high-risk genotypes." (PMID 35967115, 2022). "Polymorphisms including apolipoprotein L1 (APOL1), ATP-Binding Cassette Subfamily B Member 1 (ABCB1), Caveolin 1 (CAV1), and ATP-Binding Cassette Subfamily C Member 2 (ABCC2) have been shown to affect graft survival, hypertension, and calcineurin-induced nephrotoxicity." (PMID 28507980, 2017).
Hypertension (continued). "Whilst hypertension is a known contributor to the progression of CKD, the presence of elevated blood pressure may in these patients evidence underlying genetic or developmental pathophysiologies such as APOL1-related kidney disease or reduced nephron endowment." (PMID 38635562, 2024). "Proteins including AGT, ALB, APOL1, and UMOD had the highest disease scores (76–100% confidence) for CKD and hypertension." (PMID 38402394, 2024). "We did not see convincing evidence of hypertension in the absence of a high-salt diet, suggesting that HR APOL1 in endothelium is not sufficient for the hypertension phenotype." (PMID 41497611, 2025). "Additionally, proteins such as AGT, ALB, APOL1 and UMOD had the highest disease scores (76–100% confidence) for hypertension and CKD." (PMID 38402394, 2024). "Recent studies in AAs have identified APOL1 variants (Vs) as a major risk factor for the development and progression of non-diabetic kidney diseases including idiopathic FSGS and hypertension-attributed nephrosclerosis." (PMID 26106375, 2015). "The authors further proposed that the earliest effect of APOL1 might be on hypertension and not on the kidneys, a significant shift in our understanding of the disease." (PMID 40001508, 2025). "Because both hypertension and glucose elevation remain significant determinants of the progression of CKD, effective management of these parameters is of cardinal importance irrespective of the APOL1 risk allele genotype." (PMID 40001508, 2025). "The local team opted to include the one-time notification alert but combined it with the alert for APOL1-positive patients with a normal albumin/creatinine ratio and hypertension, which provided the same general recommendation and did not present follow-up actions." (PMID 34071920, 2021). "Since several clinical reports have shown that controlling hypertension does not consistently slow the progression of AMKD, this has led to a formulation wherein APOL1-RRVs primarily lead to kidney injury with accompanying hypertension." (PMID 40001508, 2025).
focal segmental glomerulosclerosis (74 papers, 2012 to 2026). A renal disorder characterized by sclerotic lesions in the glomeruli. "As an example, a recent phase-IIa study demonstrated that inaxaplin, a small-molecule compound that inhibits APOL1 function, reduced proteinuria in participants with two APOL1 variants and focal segmental glomerulosclerosis." (PMID 39857298, 2025). "Notable genetic variations include the APOL-1 gene polymorphism, which is linked to focal segmental glomerulosclerosis, HIV nephropathy, and diabetic nephropathy." (PMID 40546627, 2025). "APOL1 kidney disease can be rapid in onset with heavy proteinuria, associated with viral infections and categorized pathologically as collapsing focal segmental glomerulosclerosis." (PMID 40940784, 2025). "In this study, we identified a novel APOL1 mutation (c.C815T, p.T272I) in Chinese patients with focal segmental glomerulosclerosis (FSGS)." (PMID 40948471, 2025). "The knowledge that individuals with APOL1 HRG have increased risk of developing idiopathic focal segmental glomerulosclerosis, including with collapsing variant, predates the COVID-19 pandemic." (PMID 39291186, 2024). "There is a robust association between Apolipoprotein L1 gene variants found only on African chromosomes resulting in an increased probability of developing focal segmental glomerulosclerosis and HIV-associated nephropathy." (PMID 36944928, 2023). "A recent clinical trial demonstrated that the small molecule drug inaxaplin significantly reduced proteinuria in patients with APOL1-associated focal segmental glomerulosclerosis." (PMID 37925499, 2023). "Post-mortem kidney analyses disclosed acute tubular injury in almost all cases and less frequently thrombi and collapsing segmental and focal glomerulosclerosis associated with the APOL1 variant." (PMID 35957939, 2022). "Patients carrying genetic variants of the APOL1 gene, G1 and G2, have an increased risk of developing several forms of kidney disease, including focal segmental glomerulosclerosis (FSGS) and HIV-associated nephropathy (HIVAN)." (PMID 34442464, 2021). "Apolipoprotein L1 (APOL1) is a protein-coding gene that is associated with focal segmental glomerulosclerosis and glomerulonephritis." (PMID 33816503, 2021). "APOL1 gene variants are strongly associated with risk for focal segmental glomerulosclerosis (FSGS), HIV-associated nephropathy (HIVAN), and hypertension-attributed kidney disease (arterionephrosclerosis)." (PMID 32854642, 2020). "Two common variant alleles of apolipoprotein L1 (ApoL1) in the African-American population were recently identified as risk factors for focal segmental glomerulosclerosis (FSGS) and ESRD." (PMID 31470591, 2019). "Genetic variants in APOL1 have been identified as significant determinants of renal complications in individuals of African descent, such as focal segmental glomerulosclerosis, human immunodeficiency virus-associated nephropathy, and lupus nephritis, and have also been extensively studied in SCD." (PMID 38791464, 2024). "In addition, genetic polymorphism of the APOL1 gene is also considered a high-risk genetic variant for developing collapsing glomerulopathy- a morphological variant of focal segmental glomerulosclerosis in African American descent or black population." (PMID 34925984, 2021). "To evaluate the role of macrophages in AMKD, we examined kidney biopsies of individuals diagnosed with focal segmental glomerulosclerosis (FSGS) in the context of a high-risk APOL1 genotype." (PMID 40501951, 2025). "The APOL1 high-risk genotype, a major genetic contributor to focal segmental glomerulosclerosis (FSGS), has been shown to alter tRF expression profiles in podocytes." (PMID 41244208, 2025). "African Americans carrying two copies of APOL1 G1 or G2 kidney risk alleles (referred to herein as APOL1 variant alleles) have a sevenfold increased risk for nondiabetic end-stage kidney disease and a 17-fold increased risk for focal segmental glomerulosclerosis, respectively." (PMID 33674766, 2021).
focal segmental glomerulosclerosis (continued). "Inclusion is particularly important for patients from populations where APOL1 risk alleles are enriched (e.g. West-African ancestry), especially when presenting with clinical features such as proteinuria or focal segmental glomerulosclerosis (FSGS) on biopsy." (PMID 40459916, 2025). "This high level of APOL1 expression subsequently causes podocyte loss by either cell death or detachment leading to the prototypical pathology seen in APOL1 kidney disease: focal segmental glomerulosclerosis (FSGS)." (PMID 40940784, 2025). "Apolipoprotein L1 (APOL1) risk variants are strongly associated with kidney diseases, including focal segmental glomerulosclerosis (FSGS), though known mutations (G1/G2) are primarily observed in African populations." (PMID 40948471, 2025). "Carriers of high-risk APOL1 alleles, specifically the G1 or G2 variants, are more prevalent in this population and have been linked to an increased incidence of primary kidney diseases such as focal segmental glomerulosclerosis (FSGS)." (PMID 41550938, 2025). "Similar protective effects of p.K264 haplotype was discovered against APOL1-mediated focal segmental glomerulosclerosis." (PMID 39291186, 2024). "Variants in the APOL1 gene, for example, are common in African populations and have been associated with an increased risk of hypertension-related nephropathy and focal segmental glomerulosclerosis (FSGS)." (PMID 39728069, 2024). "Collapsing Focal Segmental Glomerulosclerosis (FSGS) has been reported relatively frequently in African American (AA) patients with coronavirus disease 2019 (COVID-19), and it is associated almost always with Apolipoprotein L gen 1 (APOL1) high-risk variants." (PMID 37229730, 2023). "Podocytes have also been reported to express apolipoprotein L1, an important component of HDL, whose gene polymorphism is associated with focal segmental glomerulosclerosis (FSGS)." (PMID 36123608, 2022). "Previous reports indicate that interferon gamma (IFN-γ), which is produced in response to HIV infection, is a potent inducer of APOL1 expression in vitro and that IFN-γ treatment can cause collapsing focal segmental glomerulosclerosis (FSGS) in humans with a high-risk APOL1 genotype." (PMID 34350953, 2021). "Kidney sections of membranous glomerulonephritis (MGN) and focal segmental glomerulosclerosis (FSGS) showed a marked decrease of the APOL1 expression." (PMID 27138898, 2016). "rs2239785 is a missense variant in APOL1 that has been previously reported to be linked with risk for nondiabetic nephropathy and focal segmental glomerulosclerosis." (PMID 39163132, 2024). "Indeed, APOL1 is associated with an increased risk of CKD, including end-stage kidney disease (ESKD), focal segmental glomerulosclerosis (FSGS), and HIV-associated nephropathy (HIVAN), specifically in individuals with sub–Saharan African ancestry." (PMID 35159001, 2022). "In addition, modifications of the apolipoprotein L1 (APOL1) gene have known links with the focal segmental glomerulosclerosis, which may affect endosomal trafficking and/or block mitophagic flux, eventually leading to podocyte injury." (PMID 38397444, 2024). "Patients carrying APOL1 risk alleles (G1 and G2) have a higher risk of developing Focal Segmental Glomerulosclerosis (FSGS); we hypothesized that escalated levels of miR193a contribute to kidney injury by activating renin–angiotensin system (RAS) in the APOL1 milieus." (PMID 39766282, 2024). "Two coding alleles within the APOL1 gene, G1 and G2, are found almost exclusively in individuals genetically similar to West African populations and contribute substantially to the pathogenesis of nondiabetic kidney disease, focal segmental glomerulosclerosis, and HIV-associated nephropathy." (PMID 39163132, 2024).
focal segmental glomerulosclerosis (continued). "A clinical trial aimed to evaluate the efficacy, safety and pharmacokinetics of oral APOL1 inhibitor (VX-147) is ongoing in patients with FSGS and APOL1 G1/G1, G2/G2 or G1/G2 genotypes (NCT04340362, Phase 2a Study of VX-147 in Adults With APOL1-mediated Focal Segmental Glomerulosclerosis)." (PMID 40755967, 2025).
COVID-19 (44 papers, 2020 to 2025). A disease caused by infection with severe acute respiratory syndrome coronavirus 2. "A plethora of cases have identified a temporal link between COVID-19 and cFSGS, particularly in the African-American population, with a higher incidence and poorer prognosis among high-risk apolipoprotein L1 (APOL1) variants." (PMID 40552181, 2025). "Among African Americans hospitalised with COVID-19, carriage of two high-risk APOL1 variants has been associated with increased AKI severity and death." (PMID 38360481, 2024). "There is growing evidence that carriage of two high-risk variant APOL1 alleles is associated with adverse outcomes in COVID-19." (PMID 38360481, 2024). "Among 53 African American patients with collapsing FSGS associated with COVID-19, 48 had high-risk APOL1 variants and five had low-risk APOL1 variants." (PMID 37229730, 2023). "A recent study of COVID-19 patients in African reveals that there presents the correlation of APOL1 kidney risk variants with high AKI incidence." (PMID 37789254, 2023). "In summary, non-African American patients, collapsing FSGS has been reported rarely as a complication of COVID-19, and it can be associated with high-risk and a minority of low-risk APOL1 variants." (PMID 37229730, 2023). "Among COVID-19 patients, collapsing glomerulopathy is the most common glomerular disease associated with Apolipoprotein L1 (APOL1) gene polymorphisms, especially in African Americans." (PMID 36851366, 2023). "In summary, human iPSC-derived kidney micro-organoids cultured with COVID-19–induced cytokines showed robust upregulation of pathogenic G1G2 APOL1 protein and the expression was blocked by inhibition of JAK/STAT signaling." (PMID 35472001, 2022). "APOL1 mutations have been detected in many patients with COVID-19, which suggested that the virus is a potential secondary trigger for glomerular damage." (PMID 35308512, 2022). "There has been an emergence of these cases among African American patients with COVID-19, especially those with the apolipoprotein L1 (APOL1) allele." (PMID 36465729, 2022). "Together, these results support the conclusion that COVID-19–induced cytokines trigger JAK/STAT/APOL1 signaling, which, in turn, causes podocyte injury and loss." (PMID 35472001, 2022). "These murine disease models suggest that the mechanism that underlies COVID-19–induced APOL1 expression would be a potential therapeutic target for COVAN." (PMID 35472001, 2022). "We present a case of an African American patient with COVID-19 who tested positive for the APOL1 allele in the setting of acute renal deterioration." (PMID 36465729, 2022). "It raises a question about safety of supplemental IFNs as COVID-19 therapy in Black and Hispanic individuals who carry high-risk APOL1 genotypes." (PMID 35472001, 2022). "The increased risk of collapsing glomerulopathy in patients with COVID-19 is related to the high-risk apolipoprotein L1 (APOL1) genotype (G1, G2)." (PMID 35145920, 2021). "A recent study observed that APOL1 risk variants are associated with a higher incidence of sepsis and increased disease severity in patients with COVID-19." (PMID 35095882, 2021). "While acute tubular necrosis is correlated with COVID-19 severity, the pattern of glomerular injury is intimately associated with the expression of APOL1 risk variants." (PMID 34185186, 2021). "Collapsing glomerulopathy is a severe form of kidney disease related to APOL1 and has been described as COVID-19–associated glomerulopathy." (PMID 33195337, 2020). "Homozygosity for high-risk APOL1 alleles is present in 14% of African Americans, who collectively represent 12.9% of the US population but have suffered an estimated 25.1% of U.S. COVID-19 deaths." (PMID 33109103, 2020). "Additionally, individuals with high-risk APOL1 genotypes are more likely to develop COVID-19–associated collapsing glomerulopathy (COVAN), particularly among African Americans." (PMID 40963897, 2025).